NDRG2 (NDRG family member 2)
Diseases named in the same sentence as NDRG2 in open-access papers (continued):
Sharing a sentence is not in itself a finding about the gene and the disease.
renal carcinoma (3 papers, 2010 to 2021). A carcinoma arising from the epithelium of the renal parenchyma or the renal pelvis. "In RCC, hypoxia induced upregulation of miR-346 and N-myc downstream-regulated gene 2 (NDRG2) inhibition in renal cancer cells." (PMID 35004677, 2021). "We found that NDRG2 can inhibit the proliferation of the renal carcinoma cells and induce arrest at G1 phase." (PMID 20673333, 2010). "In the present work, we found that forced expression of NDRG2 can inhibit the proliferation of the renal carcinoma cells and induce arrest at G1 phase." (PMID 20673333, 2010). "This recombinant adenovirus had a high transfection on A-498 renal cancer cells and successfully expressed NDRG2 at a high level." (PMID 20673333, 2010). "We found that NDRG2 significantly inhibited renal cancer cell proliferation." (PMID 20673333, 2010). "Then we demonstrated that NDRG2 tumor-suppressor activity is mediated by the inhibition of cell cycle progression with increased accumulation of cancer cells in G1-phase and a corresponding reduction of cells in the S-phase of the cell cycle in the A-498 renal cancer cells." (PMID 20673333, 2010). "Also clearly in our studies, NDRG2 induced renal cancer cell apoptosis." (PMID 20673333, 2010). "Overexpression of NDRG2 upregulated the expression of pVHL along with downregulation of HIF-1α and attenuated proliferation and invasion in renal cancer cells." (PMID 34013046, 2021). "Our results show that enforced NDRG2 expression significantly inhibited RCC cell growth, and induced apoptosis in human renal carcinoma cells." (PMID 20673333, 2010).
astrocytoma (2 papers, 2016 to 2025). "In grade 4 astrocytomas, NDRG2 expression is frequently downregulated, contributing to tumour progression, increased invasiveness, and reduced apoptosis." (PMID 41179304, 2025). "NDRG2 expression is positively correlated with the life span of astrocytoma patients." (PMID 26506239, 2016).
depression (2 papers, 2012 to 2019). "In addition to cell proliferation, differentiation, and transmembrane transports, NDRG2 also participates in stress responses, depression, ischemic diseases, and neurodegenerative disorders." (PMID 31341912, 2019). "Data on the expression of GFAP and NDRG2 after chronic social stress may shed light on the role of astrocytes in depression." (PMID 22610521, 2012).
gallbladder carcinoma (2 papers, 2012 to 2016). "Very recently, reduction of FXR expression was demonstrated in cholangiocarcinoma and biliary tract carcinoma and in tumor versus normal liver tissue from HCC patients and NDRG2 expression was found downregulated in gallbladder carcinoma with poor outcome." (PMID 23056173, 2012).
histiocytic lymphoma (2 papers, 2018 to 2020). "In histiocytic lymphoma U937 cells, NDRG2 could modulate NOX5-ROS-PKR pathway-regulated Bak-to-Mcl-1 ratio to increase the sensitivity to cisplatin." (PMID 32345304, 2020).
ischemia reperfusion injury (2 papers, 2013 to 2023). Adverse functional, metabolic, or structural changes in ischemic tissues resulting from the restoration of blood flow to the tissue (reperfusion), including swelling; hemorrhage; necrosis; and damage from free radicals. "However, it is still uncertain whether NDRG2 participates in cellular apoptosis induced by ischemia-reperfusion injury in brain." (PMID 23451161, 2013).
lentivirus infection (2 papers, 2015 to 2017). Virus diseases caused by the Lentivirus genus. "We further knockdown NDRG2 by lentivirus infection in MCF-7 cells." (PMID 28423695, 2017).
metastatic tumors (2 papers, 2018 to 2020). "Thus, c-Myc induction of ASCT2 is dependent on Akt activation in response to the loss of NDRG2 in metastatic tumors." (PMID 33162818, 2020). "Thus, we demonstrate that the generations of EMT and glutamine-dependent phenotypes are attributed to the loss of NDRG2 expression in metastatic tumors, and the gain of NDRG2 function can suppress metastatic tumor survival through the blockage of glutaminolysis." (PMID 33162818, 2020). "Thus, the generation of glutamine-dependent phenotype in metastatic tumor is probably attributable to NDRG2 downregulation." (PMID 33162818, 2020). "To fully address the differences of glutamine metabolism between primary and metastatic tumors related to NDRG2, we carried out RNA-seq assay to determine the gene expression profile alterations in MC3 cells with or without NDRG2 overexpression." (PMID 33162818, 2020).
osteoarthritis (2 papers, 2021 to 2023). A noninflammatory degenerative joint disease occurring chiefly in older persons, characterized by degeneration of the articular cartilage, hypertrophy of bone at the margins and changes in the synovial membrane. "Previous research has identified N-myc downstream-regulated gene 2 (NDRG2) as one of the differentially expressed genes common to rat models of osteoarthritis (OA) and human OA." (PMID 34551684, 2021). "We therefore consider these approaches, including the study of osteoarthritis development in surgical and aging models, as the next steps in our quest to understand the role of NDRG2, WSB1, JMJD6, TSPYL2, HMGB2 and PPP1R15A in osteoarthritis and their inner mechanistic links." (PMID 37033917, 2023).
pituitary adenomas (2 papers, 2017 to 2025). "The different NDRG2 promoter methylation and expression levels in PA samples showed tumor heterogeneity and indicates a potential role of this gene in pituitary adenoma pathogenesis, but the corresponding details require intensive research." (PMID 28390436, 2017). "Finally, we analyzed the relationship between NDRG2 gene promoter methylation, mRNA expression, and invasiveness of 71 pituitary adenomas (51 invasive and 20 noninvasive)." (PMID 28390436, 2017). "The mechanism of NDRG2 expression in pituitary adenoma proliferation and invasion has not yet been reported, making it necessary to further elucidate the role of NDRG2 gene in pathogenesis of PA." (PMID 28390436, 2017). "Several studies have shown N-myc downstream regulated gene 2 (NDRG2) as a tumor suppressor gene, but the role of NDRG2 gene in pituitary adenoma pathogenesis has not been elucidated." (PMID 28390436, 2017). "The lowest NDRG2 expression was detected in PAs secreting more than one hormone, and the highest in PRL-secreting and non-secreting pituitary adenomas." (PMID 28390436, 2017).
renal fibrosis (2 papers, 2020 to 2025). A final common manifestation of a wide variety of chronic kidney diseases characterized by glomerulosclerosis and tubulointerstitial fibrosis. "In the progression of renal fibrosis, ROS can promote hypermethylation of the NDRG2 promoter, which is consistent with findings in diabetic retinopathy, where inhibiting DNMT1 was shown to reduce ROS levels." (PMID 40553255, 2025).
Senile plaques (2 papers, 2011 to 2019). Senile plaques are extracellular deposits of amyloid in the gray matter of the brain. "Up-regulation of NDRG2 in cortical pyramidal neurons and senile plaques of Alzheimer's patients, suggested it was associated with ageing." (PMID 22043305, 2011). "DAPK1 is activated by senile plaques and ceramide and has a higher expression in human AD brain samples, as well as NDRG2-phosphorylation levels." (PMID 31485792, 2019). "Expression of NDRG2 was localized to cortical pyramidal neurons, dystrophic neurons, and senile plaques, which are all affected by AD." (PMID 31485792, 2019).
squamous carcinoma (2 papers, 2009 to 2013). "The mRNA level of NDRG2 was positively correlated with differentiation grade in both squamous carcinoma and adenocarcinoma; in contrast, NDRG2 level was negatively correlated with UICC stage." (PMID 23307246, 2013).
thyroid tumor (2 papers, 2008 to 2010). A benign or malignant neoplasm affecting the thyroid gland. "Because Ndrg2 expression is decreased in many types of cancer tissues, a preliminary analysis on Ndrg2 expression in thyroid tumors was performed using a tissue microarray." (PMID 18940011, 2008).
acromegaly (1 paper, 2017). Acromegaly is an acquired disorder related to excessive production of growth hormone (GH) and characterized by progressive somatic disfigurement (mainly involving the face and extremities) and systemic manifestations. "Therefore, there is need for intensive research to confirm our findings and justify the hypothesis that NDRG2 could be a diagnostic marker for diagnosis of prolactinoma and acromegaly in PAs." (PMID 28390436, 2017). "Nevertheless, NDRG2 expression was increased with diagnoses of prolactinoma and decreased with diagnoses of acromegaly, compared to patients with other symptoms (p < 0.05)." (PMID 28390436, 2017). "The NDRG2 mRNA expression was significantly lower in the case of acromegaly (GH and IGF-1 hypersecretion) than in other diagnoses of PAs (p < 0.05)." (PMID 28390436, 2017). "Our study has revealed that in the case of acromegaly, NDRG2 gene mRNA expression is significantly lower than in other diagnoses of PAs." (PMID 28390436, 2017). "Our data have revealed that in the case of acromegaly, NDRG2 gene mRNA expression is significantly lower than in other diagnosis of PAs and PA that secretes hormones GH and IGF-1 hormones have low NDRG2 gene expression level as well." (PMID 28390436, 2017).
acute myeloid leukemia (1 paper, 2019). Acute myeloid leukemia (AML) is a group of neoplasms arising from precursor cells committed to the myeloid cell-line differentiation. "In this study, we used U937 cells, which do not express NDRG2, to investigate whether NDRG2 affects cancer drug sensitivity, because the acute myeloid leukemia cell line, U937, is relatively resistant to As2O3." (PMID 31121982, 2019).
age (1 paper, 2011). A temporal measurement of the time period elapsed since an identifiable point in the life cycle of an organism. "Since the role of this gene in senescence is limited, we have investigated the potential role of NDRG2 in human lens epithelial cells (HLECs), a paradigm implicated in age-related cataract." (PMID 22043305, 2011). "NDRG2-mediated affects in HLECs may associate with age-related cataract formation." (PMID 22043305, 2011). "In order to determine whether there are differential expressions of NDRG2 between age-related cataract and normal lenses, we examined NDRG2 in HLECs adhering to anterior capsules of lenses at both mRNA and protein levels." (PMID 22043305, 2011).
Age-related cataract (1 paper, 2011). A type of cataract (opacification of the lens) that forms during the course of aging. "Furthermore, the expression of NDRG2 from age-related cataracts was up-regulated 2-fold at both mRNA and protein levels compared with the clear lenses." (PMID 22043305, 2011). "In addition, we also found expression of NDRG2 in HLECs from age-related cataracts was higher than clear lenses at both mRNA and protein levels." (PMID 22043305, 2011). "Since environmental factors such as oxidative stress have been implicated in the formation of age-related cataract, and H2O2 is the major oxidant involved in cataract formation, we observed the response of NDRG2-infected cells to various concentrations of H2O2." (PMID 22043305, 2011).
attention deficit-hyperactivity disorder (1 paper, 2019). A disorder characterized by a marked pattern of inattention and/or hyperactivity-impulsivity that is inconsistent with developmental level and clearly interferes with functioning in at least two settings (e.g. at home and at school). "In mice and humans, NDRG2 participates in the development of attention-deficit/hyperactivity disorder (ADHD), a disease associated with the locomotion center in the cerebral cortex." (PMID 31341912, 2019).
brain edema (1 paper, 2025). Increased intracellular or extracellular fluid in brain tissue. "Investigations also demonstrated possible neuroprotective roles of NDRG2, as demonstrated by the ability of NDRG2 expression in male mice to prevent ischemic brain edema." (PMID 40378957, 2025).
brain glioma (1 paper, 2016). A malignant glioma that involves the brain. "Until recently, investigations found that NDRG4 was overexpressed in human brain glioma and might promote tumor progression, indicating an oncogenetic role of NDRG4, which was opposed to the role of NDRG2 in human brain malignancy." (PMID 26515606, 2016).
brain tumours (1 paper, 2024). "A novel tumour suppressor gene, NDRG2, is downregulated in almost all cases of ATL, as well as in the majority of various cancers, such as liver, lung, colorectal, oral, and brain tumours." (PMID 38474089, 2024).
cancers of the nervous system (1 paper, 2019). "In the context of nervous system cancers, NDRG1, NDRG2, and NDRG4 have been described to be tumor suppressor genes, although some results are not consistent throughout different studies." (PMID 31485792, 2019).
cardiac ischemia (1 paper, 2020). "Finally, NDRG2 has been implicated with the stress response in cardiac ischemia/reperfusion." (PMID 32433643, 2020).
cardiomyopathy (1 paper, 2020). A disease of the heart muscle or myocardium proper. "NDRG2 can also activate glycogen synthase kinase 3β (GSK-3β), impacting β-catenin signaling and potentially contributing to cardiomyopathy establishment as the GSK3 family has been implicated in the regulation of cardiac remodeling downstream of the PI3K–Akt pathway." (PMID 32433643, 2020).
cataract (1 paper, 2011). Partial or complete opacity of the crystalline lens of one or both eyes that decreases visual acuity and eventually results in blindness. "Bands at around 41 kDa, reacted with anti-Ndrg2 goat polyclonal antibody were detected in both the cataracts and clear lenses (left)." (PMID 22043305, 2011). "In the epithelia of cataracts, moderate staining for Ndrg2 was seen in the whole tissues with many strongly stained epithelial cells scattered in them." (PMID 22043305, 2011).
Chagas disease (1 paper, 2020). A parasitic infection caused by Trypanosoma cruzi. "Bioinformatic analysis of kinase activity provided substantial evidence for the activation of NDRG2 and JNK/p38 kinases during Chagas disease." (PMID 32433643, 2020).
chronic hepatitis (1 paper, 2012). An active inflammatory process affecting the liver for more than six months. "Neither FXR nor NDRG2 seemed significantly down-regulated in the combined set of 13 tested non-HCC liver-disease cDNA samples originating from patients with liver cirrhosis (n = 5), fatty liver (n = 5) and chronic hepatitis (n = 3) compared to “normal” liver." (PMID 23056173, 2012).
colorectal adenoma (1 paper, 2007). An adenoma that arises from the colon or rectum. "Future studies are needed to address whether NDRG2 down-regulation is a cause or consequence of the progression of colorectal adenomas to carcinoma." (PMID 17935612, 2007). "Using real-time RT-PCR we have measured the levels of NDRG2 mRNA in colonic tissue from healthy individuals and from individuals with colorectal adenomas or carcinoma." (PMID 17935612, 2007). "By examining affected and normal tissue from individuals with colorectal adenomas and carcinomas, as well as in healthy individuals, we aim to determine whether and at which stages NDRG2 down-regulation occurs during colonic carcinogenesis." (PMID 17935612, 2007).
COVID-19 (1 paper, 2024). A disease caused by infection with severe acute respiratory syndrome coronavirus 2. "Further research is needed to fully understand the contribution of NDRG2 and other identified genes and transcripts in modulating the immune response in COVID-19." (PMID 37918965, 2024). "Interestingly, the AUC was also associated with NDRG2, a target of HIF-1a signaling and regulator of apoptosis, suggesting NDRG2 as a possible regulator of AUC in the COVID-19 patients." (PMID 37918965, 2024). "The direct role of the NDRG2 gene in immune response remains unclear, but previous studies have suggested its involvement in NF-B inhibition and its potential relevance to severe COVID-19." (PMID 37918965, 2024).
Cushing syndrome (1 paper, 2017). Cushing's syndrome (CS) encompasses a group of hormonal disorders caused by prolonged and high exposure levels to glucocorticoids that can be of either endogenous (adrenal cortex production) or exogenous (iatrogenic) origin. "Clinical factors, such as: age, gender, relapse and diagnoses of Cushing syndrome were of no significance for NDRG2 promoter methylation and mRNA expression levels, as well as secreting or non-secreting PAs and the invasiveness of PAs." (PMID 28390436, 2017).
deep venous thrombosis (1 paper, 2025). "We found significant associations between eQTL-mediated changes in TMEM88, NDRG2 and FZD5 expression with myocardial and vascular traits including heart rate and deep venous thrombosis." (PMID 39904980, 2025).
dementia (1 paper, 2018). Loss of intellectual abilities interfering with an individual's social and occupational functions. "Within TCX, expression of GLUD1 (t = −2.255, padj = 0.036) and NDRG2 (t = −2.120, padj = 0.048) were significantly lower in subjects with dementia versus dementia-free subjects." (PMID 30120299, 2018).
heart failure (1 paper, 2025). Inability of the heart to pump blood at an adequate rate to meet tissue metabolic requirements. "NDRG2 has been shown to inhibit β-catenin target genes in heart, brain and liver development, as well as being relevant in heart failure contexts." (PMID 39904980, 2025).
hypogonadism (1 paper, 2022). A disorder characterized by decreased function of the gonads. "Studies have shown that lncRNA MIR22HG promotes LCs apoptosis by acting as ceRNA for miRNA-125a-5p that targets NDRG2 in late-onset hypogonadism." (PMID 36090173, 2022).
invasive breast carcinoma (1 paper, 2016). A carcinoma that infiltrates the breast parenchyma. "However, invasive breast carcinomas showed a significant (P<0.001) reduction or complete loss (median IRS < 6) of NDRG2 expression in 80% (128/161) of cases." (PMID 27400234, 2016).
invasive ductal carcinoma (1 paper, 2016). "Furthermore, we demonstrated a reduced NDRG2 mRNA expression in invasive ductal carcinoma (IDC) with regard to invasive lobular breast cancer (ILC)." (PMID 27400234, 2016).
laryngeal carcinoma (1 paper, 2022). Carcinoma that arises from the laryngeal epithelium. "For example, the tumor suppressor NDRG1 and NDRG2 present highly methylated and low protein expression status in laryngeal cancer, suggesting that abnormal methylation on the NDRG1/2 promoter region may be an early event in laryngeal cancer initiation." (PMID 35287752, 2022).
latent infection (1 paper, 2025). "The downregulated DETs of Sept4, Kcng4, Unc13c, and Prkcg in the WH6 group, which are related to synaptic transmission, and Ndrg2 and Arc in the LHG group, which are related to neurodegenerative diseases, were selected to be the key candidates in the latent infection phase." (PMID 40420177, 2025).
leukemia (1 paper, 2010). A malignant (clonal) hematologic disorder, involving hematopoietic stem cells and characterized by the presence of primitive or atypical myeloid or lymphoid cells in the bone marrow and the blood. "Ndrg2 expression is induced by WT1, a transcriptional regulator frequently expressed in leukemias." (PMID 20098702, 2010).
Lewis lung carcinoma (1 paper, 2018). "To determine the role of NDRG2 in the liver microenvironment during cancer liver metastasis, we established CMT93 and Lewis lung carcinoma (LLC) cell liver metastasis model." (PMID 29445150, 2018).
liver diseases (1 paper, 2012). "The expression of FXR, NDRG2 and SHP mRNAs are significantly reduced in all tumor stages when compared to “normal” and to liver tissue from non-malignant liver disease." (PMID 23056173, 2012).